PRKN (parkin RBR E3 ubiquitin protein ligase)
Diseases named in the same sentence as PRKN in open-access papers (continued):
Sharing a sentence is not in itself a finding about the gene and the disease.
sleep disorder (3 papers, 2022 to 2024). A change from the patient's baseline sleeping pattern, in the hours slept and/or an alteration/dysfunction in the stages of sleep. "Another intriguing example is the association between a relatively common CNV (frequency = 0.22%) affecting exon 2 and intron 2–3 of PRKN [MIM: 602544]—a gene causing juvenile autosomal recessive Parkinson’s disease [MIM: 600116]—and sleep disorders such as insomnia and hypersomnia." (PMID 38185688, 2024).
Viral infections (3 papers, 2019 to 2024). "Viral infections usually trigger the cellular parkin RBR E3 ubiquitin protein ligase (PRKN)-dependent or receptor-mediated mitochondrial autophagy by inducing mitochondrial dysfunction, while other viruses can induce mitochondrial autophagy through their own viral proteins." (PMID 39273156, 2024). "During viral infection, phosphorylation of DNM1L (Ser616) is upregulated, promoting DNM1L recruitment to mitochondria and leading to mitochondrial fission, which initiates the PRKN-dependent mitophagy." (PMID 39273156, 2024).
Apathy (2 papers, 2022 to 2023). Apathy is a quantitative reduction of interest, motivation and the initiation and persistence of goal-directed behavior, where often the accompanying emotions, thoughts, and social interactions are also diminished. "The patient carrying PRKN deletion of exon 4, LRRK2 deletion of exon 49, and MAPT p.Asn596Lys had dominant motor disturbances (high MDS‐UPDRS score of part III), but without the presence of apathy as previously reported." (PMID 36879366, 2023).
cervical cancer (2 papers, 2021 to 2022). A primary or metastatic malignant neoplasm involving the cervix. "As reported, downregulation of PRKN had been associated with ovarian, colorectal, and cervical cancers." (PMID 36120545, 2022).
Gliosis (2 papers, 2025). Gliosis is the focal proliferation of glial cells in the central nervous system. "Gliosis has been widely reported in human post-mortem brain studies of patients with PRKN loss-of-function mutations." (PMID 38979135, 2025).
mental disorder (2 papers, 2015 to 2025). A disease that has its basis in the disruption of mental process. "Considering that oxidative stress and stressors similar to neurogenerative disorders are often present in the pathogenesis of mental disorders and suicidality, the increased expression of PRKN in suicidal deaths could be explained in several ways." (PMID 41465140, 2025).
oral cancer (2 papers, 2023 to 2025). "To examine the role of PRKN in MFTP1-mediated mitophagy, we knocked down PRKN in MFTP1-overexpressing cells, and showed that loss of PRKN inhibits CCCP-induced mitophagy in oral cancer cells." (PMID 40395309, 2023). "Moreover, knockdown of PRKN (parkin RBR E3 ubiquitin protein ligase) or PINK1 (PTEN-induced kinase 1) abolished mitophagy in MTFP1-overexpressing oral cancer cells." (PMID 40395309, 2023).
prion disease (2 papers, 2020 to 2021). A transmissible disease that is caused by a protein that is able to induce abnormal folding of normal cellular proteins, leading to characteristic spongiform brain changes, which are associated with neuronal loss without an inflammatory response. "Whereas the predominant pathogenic mutations in both SNCA and LRRK2 result in autosomal dominant pattern similarly to inherited forms of human prion diseases, other mutations (e.g., PARK2, PARK7, and PARK6) that involve PRKN, DJ-1, and PINK1 genes result in autosomal recessive patterns." (PMID 34360787, 2021).
prostate adenocarcinoma (2 papers, 2017 to 2025). "In prostate adenocarcinoma (PRAD), OPTN, PRKN, BNIP3L, PINK1, and MAP1LC3A were significantly downregulated." (PMID 39859167, 2025).
Spastic paraplegia (2 papers, 2009 to 2022). Complete loss of the ability to move the lower limbs accompanied by spasticity of the lower limbs. "In four patients, rare heterozygous RDVs were detected in other neurodegeneration-associated genes, such as PRKN (PD), LRRK2 (PD), PARK7 (PD), C19ORF12 (NBIA), SPG11 (Spastic paraplegia-SP/ALS), and PSAP (Metachromatic leukodystrophy-MLD)." (PMID 35752680, 2022).
acral melanomas (1 paper, 2022). "Our finding of recurrent germline and somatic inactivating alterations suggests that PRKN probably also functions as a tumor suppressor in acral melanoma." (PMID 35706047, 2022).
age (1 paper, 2026). A temporal measurement of the time period elapsed since an identifiable point in the life cycle of an organism. "PRKN is intricately associated with aging and age‐related diseases through diverse mechanisms." (PMID 41457744, 2026). "To investigate PRKN's role in physiological aging and age‐related diseases, we quantified PRKN protein levels in lung tissues from young controls, aged mice, and mice with IPF." (PMID 41457744, 2026).
autonomic dysfunction (1 paper, 2025). "While the results for LRRK2 were less robust after adjustment, and data on PRKN remain inconclusive due to the small sample size, our study reinforces the importance of considering genotype in the clinical evaluation of autonomic dysfunction in PD." (PMID 40904824, 2025). "This study aimed to assess the profile of autonomic dysfunction symptoms in three groups of patients with genetic PD, carrying mutations in GBA, LRRK2, and PRKN genes, compared with subjects with sporadic PD." (PMID 40904824, 2025).
breast adenocarcinoma (1 paper, 2024). "For these experiments, murine breast adenocarcinoma AT3 cells were engineered to conditionally express PRKN (TetON system) in response to Doxy (inset)." (PMID 39213189, 2024).
Buruli ulcer (1 paper, 2020). "Significant association with Buruli ulcer was reported for common variants of six of these genes: SLC11A125, PRKN, NOD2, and ATG16L126 and iNOS and IFNG27." (PMID 32313116, 2020).
chordoma (1 paper, 2025). Chordomas are rare malignant tumors arising from embryonic remnants of the notochord in axial skeleton. "Significant enrichments were identified in dedifferentiated chordoma, specifically for CARM1 (100%, p < 10−10), PRKN (66.67%, p < 10−10), and MTAP (100%, p = 0.009), suggesting these mutations may uniquely characterize dedifferentiated chordoma." (PMID 39941902, 2025).
colitis (1 paper, 2019). Inflammation of the colon. "In colitis, pharmacological induction of mitophagy through PRKN is found to inactivate inflammasomes in macrophages and ameliorate the impact of colitis." (PMID 31671556, 2019).
COVID-19 (1 paper, 2023). A disease caused by infection with severe acute respiratory syndrome coronavirus 2. "This study identified SVs impacting genes implicated in neurological functions in patients with neurological manifestations of COVID-19, of which, two SVs in PRKN and GRID2 genes are the most interesting candidates." (PMID 36671517, 2023).
dengue (1 paper, 2023). "Further investigations revealed that dengue derails the well-established pathway of flagging damaged mitochondria for elimination through mitophagy by downregulating the expression of PINK1 and PRKN/parkin, two proteins that play a crucial role in the flagging process." (PMID 40395305, 2023).
hyperlipidaemia (1 paper, 2020). "At the same time, the PRKN C-G-C-A-T-T-C haplotype was associated with an increased risk of hyperlipidaemia, whereas the interactions of the PRKN–PACRG C-G-T-G-C-T-C-A-T-C-T and C-G-T-G-T-T-C-A-T-C-T were correlated with a decreased risk of hyperlipidaemia." (PMID 32747620, 2020). "The PRKN C-G-C-A-T-T-C and PRKN–PACRG C-G-T-G-T-T-C-A-T-A-T haplotypes were associated with an increased risk of hyperlipidaemia, whereas the PRKN–PACRG C-G-T-G-C-T-C-A-T-C-T and C-G-T-G-T-T-C-A-T-C-T haplotypes provided a protective effect." (PMID 32747620, 2020). "But the carriers of the PRKN–PACRG C-G-T-G-C-T-C-A-T-C-T and C-G-T-G-T-T-C-A-T-C-T decreased the risk of hyperlipidaemia (adjusted OR = 0.172, 95% CI = 0.116–0.645, P < 0.001)." (PMID 32747620, 2020).
impulse control disorder (1 paper, 2022). A category of behaviors that can be loosely defined as the failure to resist an impulsive act or behavior that may be harmful to self or others. "Of note, at least one study demonstrated that PRKN-PD patients might be more prone to impulse control disorder (ICD); therefore, caution should be used when administering dopamine agonists and CASI." (PMID 36337703, 2022).
Lewy body diseases (1 paper, 2025). "Notably, DLB had the most splicing changes and overlap with the hPSC-derived PRKN mutant splicing changes and the splicing factor SRRM2 was affected in the mutant hPSCs and all three Lewy body diseases." (PMID 40950074, 2025).
Limb dystonia (1 paper, 2023). Focal limb dystonia is a form of focal dystonia (see this term), characterized by dystonic spasms of arm or leg muscles accompanied by repetitive, twisting movements or abnormal positions or postures. "A cohort study has reported painful limb dystonia as a symptom among PRKN pathogenic variant carriers." (PMID 38020640, 2023).
oropharyngeal squamous cell carcinoma (1 paper, 2020). "Decreased expression of PRKN has also been identified in oropharyngeal squamous cell carcinoma (OPSCC) samples compared with paired normal tissues, which is consistent with our findings." (PMID 33456497, 2020).
pemphigus (1 paper, 2025). Pemphigus is a group of rare autoimmune diseases that cause blistering of the skin and mucous membranes (mouth, nose, throat, eyes, and genitals).This conditioncan occur at any age, but often strikes people in middle or older age. "In the development and progression of pemphigus, NLRP inflammatory bodies, Caspase, IL-1 and IL-18, PRKN, and P2X are considered to be implicated." (PMID 40102153, 2025). "This suggests that the PRKN gene may play a protective role in pemphigus patients, as its normal function promotes mitochondrial health, reduces inflammatory response, and inhibits the scorch-death process." (PMID 40102153, 2025).
Prostate (1 paper, 2024). "In a first series of experiments, we crossed Transgenic Adenocarcinoma of the Mouse Prostate (TRAMP) mice, which express the SV40 large T antigen oncogene in the prostate under the control of the probasin promoter with PRKN-knockout (PRKN-KO) mice." (PMID 39213189, 2024).
proteinopathy (1 paper, 2020). "Upregulation of PRKN expression or RNAi-mediated downregulation of PINK1 levels suppressed TDP43-induced degenerative phenotype in Drosophila, indicating that PRKN and PINK1 are important components of TDP43-induced proteinopathy." (PMID 32582692, 2020).
restless legs syndrome (1 paper, 2022). A condition that occurs while resting or lying in bed; it is characterized by an irresistible urgency to move the legs to obtain relief from a strange and uncomfortable sensation in the legs. "Variants of GBA, LRRK2 and PRKN did not increase or decrease the risk and severity of excessive daytime sleepiness and restless legs syndrome in PD." (PMID 35395825, 2022).
skin cancer (1 paper, 2025). "In our study, 3/16 PRKN carriers had a positive cancer history [mostly skin cancer (non-melanoma) and other types like breast, prostate, or colorectal cancer]." (PMID 41300754, 2025).
thymoma (1 paper, 2025). A neoplasm arising from the epithelial cells of the thymus. "In addition, PRKN methylation was inversely related to its mRNA levels in thymomas (THYM)." (PMID 39859167, 2025).
uterine carcinosarcoma (1 paper, 2025). A usually aggressive malignant neoplasm arising from the uterine corpus and less often the cervix. "For example, PRKN exhibited homozygous amplifications in cancers such as uterine carcinosarcoma (UCS) and adrenocortical carcinoma (ACC)." (PMID 39859167, 2025).
X-linked dystonia-parkinsonism (1 paper, 2024). X-linked dystonia-parkinsonism (XDP) is a neurodegenerative movement disorder characterized by adult-onset parkinsonism that is frequently accompanied by focal dystonia, which becomes generalized over time, and that has a highly variable clinical course. "Similarly, transposable element insertions in the gene TAF1 are causative of X-linked dystonia Parkinsonism 6–8, and PRKN (Parkin) gene rearrangements are a known cause of early onset PD9–12." (PMID 39764002, 2024).
tumor (131 papers, 2010 to 2026). "As a tumor suppressor gene, PRKN is expressed at low levels in PC and is associated with poor prognosis." (PMID 39836601, 2025). "Clinical and epidemiological evidence strongly suggests that PRKN is an important tumor suppressor gene in several types of cancer, and low expression levels of PRKN are associated with poor prognosis." (PMID 38424181, 2024). "On the other hand, the loss of PINK1 and PRKN allows the cell cycle to proceed, meeting the metabolic demands of the tumor and promoting the progression of NSCLC." (PMID 38155968, 2023). "A previous study showed an important role for PRKN as a tumor suppression factor both in melanoma risk and progression." (PMID 37629650, 2023). "Recurrent loss-of-function mutations of PRKN occur in several cancer types where it acts as a tumor suppressor gene." (PMID 35706047, 2022). "PRKN has been found to be affected in tumor microenvironmental signaling networks with likely loss of expression in HNSCC tumor samples." (PMID 33456497, 2020). "The PRKN gene is involved in BC tumor development and growth, and loss of Parkin expression due to promoter methylation may be used as a prognostic marker for BC survival." (PMID 40941673, 2025). "Evidence also suggests that loss of PRKN function either by deletions or pathogenic mutations may be involved in tumor progression and metastasis, consistent with the patient’s stage in this study." (PMID 36005154, 2022). "In addition, we found that PRKN was tightly associated with six immune infiltrating cells, which accounted for their role in anti-tumor immunity." (PMID 35198564, 2021). "PRKN gene encodes protein parkin, which belongs to a group of proteins called E3 ubiquitin ligases, and is involved in the maintenance of mitochondria, and also act as a tumor suppressor protein." (PMID 32210791, 2020). "The study found that USP14 and BAG4 were significantly overexpressed in tumor tissues compared to normal tissues, whereas PRKN expression was markedly reduced." (PMID 40316942, 2025). "In summary, our study highlights the role of USP14 in promoting tumor progression by regulating the BAG4/PRKN-mediated mitophagy pathway." (PMID 40316942, 2025). "PRKN (cg26245302) was also hypomethylated in most tumor types, like BLCA, KICH, MESO, OV, PCPG, READ, SKC, and THYM." (PMID 39859167, 2025). "Mutation analysis also showed frequent alterations in PRKN (34%), OPTN (21%), PINK1 (28%), and SRC (15%), with implications for the tumor microenvironment." (PMID 39859167, 2025). "In fact, several independent studies have highlighted the ability of PRKN to inhibit multiple intrinsic tumor traits of metabolic reprogramming, mitotic transitions, and cell motility and invasion, all independent of mitophagy." (PMID 39213189, 2024). "Under these conditions, reintroduction of PRKN by transient transfection upregulated PRKN mRNA and protein levels in all human tumor types tested." (PMID 39213189, 2024). "Here we show that PRKN expression was low and that PRKN acts as a tumor suppressor by inhibiting the proliferation and migration of BLCA cells in a mitophagy-independent manner." (PMID 38424181, 2024). "Further bioinformatics analysis of this dataset showed that PRKN upregulated DNA damage and cell death responses, whereas intrinsic tumor traits of glycolysis, eIF2-α protein translation, and cell cycle were downregulated." (PMID 39213189, 2024). "Addition of Doxy to the drinking water of tumor-bearing mice induced high levels of intratumoral PRKN expression, determined by IHC, accompanied by significant inhibition of tumor growth." (PMID 39213189, 2024). "Consistent with this, PRKN inhibition of tumor growth depended on a competent immune system and was abolished in immunocompromised Nu/Nu mice." (PMID 39213189, 2024). "As a result, decitabine-induced reexpression of endogenous PRKN potently upregulated IFN gene expression in all tumor types tested." (PMID 39213189, 2024).